IL10 (interleukin 10)
Diseases named in the same sentence as IL10 in open-access papers (continued):
Sharing a sentence is not in itself a finding about the gene and the disease.
intestinal infection (13 papers, 2012 to 2025). "IL-10 has been shown to play a protective role in intestinal infections by reducing inflammation and preventing tissue damage." (PMID 38956671, 2024). "We have seen this phenomenon before with Eimeria intestinal infection and the IL-10 response." (PMID 34928716, 2022). "With respect to gastrointestinal infections, the EPS produced by B. longum BCRC 1464 has been shown to possess antimicrobial activity against pathogens and immune-modulating activity, which causes release of the anti-inflammatory cytokine IL-10." (PMID 27656878, 2016). "The IL-10 axis is pivotal in defining the outcome of intestinal infection." (PMID 24823621, 2014).
leukopenia (13 papers, 2015 to 2026). "It is known that anti-inflammatory interleukins, such as IL-10, inhibit the expression of endothelial adhesion molecules and prevent the leukocyte extravasation, thereby preventing leukopenia." (PMID 34768958, 2021). "Another contributing factor may be the severe leukopenia caused by the virus, with a significant decrease in the number of CD4 and CD8 lymphocytes and elevation of interleukins (IL-2R, IL-6, IL-10, TNF-alpha) and other inflammatory markers." (PMID 35205852, 2022). "Severity of CLP in cGAS-/- mice was less severe than in wildtype (WT) mice, as indicated by mortality, serum LPS, cfDNA, leukopenia, cytokines (TNF-α, IL-6 and IL-10), organ histology (lung, liver and kidney) and spleen apoptosis." (PMID 34768881, 2021).
neutropenia (13 papers, 2015 to 2025). A decrease in the number of neutrophils found in the blood. "Other markers such as SDF-1, IL-10, and IL-17A are associated with neutropenia and prolonged anemia." (PMID 39253080, 2024). "For biomarkers not included in CAR-HEMATOTOX but confirmed by clinical studies to be altered, perturbations in stromal cell-derived factor (SDF-1) levels may be associated with late-onset neutropenia, and high levels of IL-10 and IL-17A are risk factors." (PMID 39253080, 2024). "In addition to the elevated levels of TNFα and IL-6, we also observed that IL-10 was enhanced by neutropenia during LPS-induced inflammation at both time points investigated." (PMID 40534875, 2025). "Furthermore, lymphocytopenia and neutropenia due to bone marrow invasion additionally hamstring immunity, while cytokines excreted by malignant cells (e.g., IL-6, IL-10, TGF-b) impair T-cell response to infection." (PMID 39065149, 2024). "The gender, age, neutropenia, specimen distribution, CMT, and mNGS positivity; CRP, PCT, IL-6, and IL-10 levels; and the agreement rate of mNGS with clinic were all comparable between the two groups." (PMID 35391735, 2022). "A statistically non-significant increasing of IL-10 in patients with neutropenia was noted in our study." (PMID 28692671, 2017).
pemphigus (13 papers, 2008 to 2026). Pemphigus is a group of rare autoimmune diseases that cause blistering of the skin and mucous membranes (mouth, nose, throat, eyes, and genitals).This conditioncan occur at any age, but often strikes people in middle or older age. "A previous study showed that increased IL-4 and IL-10 are involved in T cells induction and autoimmune phenomena of pemphigus vulgaris and pemphigus foliaceous." (PMID 41446688, 2026). "Bregs isolated from PBMCs of patients with pemphigus secreted normal levels of IL10 after ex vivo stimulation but showed compromised capacity of producing IL10 after long-term stimulation, which can occur in vivo during disease progression." (PMID 38203754, 2024). "CD24hiCD38hi B cells from individuals with pemphigus produced less IL-10 after long-term stimulation and had a worse capacity for inhibiting Th1 responses." (PMID 36591309, 2022). "Upregulation of the Th2 cytokines IL-4, IL-5, IL-10, and IL-13 has been described in pemphigus patients." (PMID 27304671, 2016). "One of the four studies compared the titer of specific antibodies for pemphigus between groups, as well as the levels of interleukin-10 (IL-10), interferon-gamma (IFN-γ), and soluble interleukin-2 receptor (slL-2R)." (PMID 25793005, 2015). "IL-10 concentration in serum was also significantly lower inpatients in clinical remission when compared to the active ones and its valuescorrelated with pemphigus antibodies titers." (PMID 18584045, 2008). "In a study on rituximab-treated pemphigus patients, Bregs restored their IL10-secreting capacity in patients with complete remission, but not in no response and incomplete remission, thus supporting the idea of a significant role of B10 cells in pemphigus pathogenesis." (PMID 38203754, 2024). "TNF- α, IL-6, IL-15, IL-10, IL-12, are involved in the mechanism of pemphigus lesions formation." (PMID 36613766, 2022). "Interestingly, in contrast to pemphigus patients IL-10-producing CD4+ T cells were significantly reduced in MG compared to HC." (PMID 26872212, 2016). "So we cannot fully exclude that the increased number of IL-10-producing CD4+ T cells in pemphigus patients may at least partly represent a population of type 1 regulatory T cells that are in transition to Th17 cells as it has been already shown in other inflammatory skin diseases." (PMID 26872212, 2016). "One systematic review of cytokine research in pemphigus revealed elevated levels of TNF-α, TGF-β, interleukin (IL)-8, IL-10, IL-12, IL-17, and IL-21, along with reduced levels of IL-2 and IL-23." (PMID 39463588, 2024). "In contrast to untreated patients or patients who did not react to therapy, pemphigus patients who responded to treatment with the B cell-depleting agent rituximab had higher frequencies of CD24hiCD38hi B cells and IL-10 production." (PMID 36591309, 2022). "Remarkably, active pemphigus patients exhibited slightly augmented subpopulations of IL-10-producing CD4+ T cells unlike the MG patients who showed reduced percentages of these cells compared to HC." (PMID 26872212, 2016).
pertussis (13 papers, 2010 to 2025). A contagious bacterial respiratory infection caused by Bordetella pertussis. "Allele frequencies and OR for the VDR, TNFα, IL17, MBL2 and IL10 SNPs in the pertussis patient group and control group." (PMID 26894582, 2016). "For pertussis with compromised seroprotective titers in all the study groups, a significant association with gestation age, monocyte, and plasma levels of IL-6, IL-10, and IL-2 was found in univariate analysis, but plasma IL-6 levels emerged to be the significant parameter in multivariate analysis." (PMID 33968011, 2021). "The excessive activation of neutrophils (as characterized by IL-8), coupled with IL-10-mediated immunosuppression and impaired Th1 responses, collectively forms the critical immunological basis for the progression of pertussis to severe disease." (PMID 41334407, 2025). "One-month post-primary pertussis vaccination, infants from vaccinated pregnancies still had lower IL-10 responses to B. pertussis, as well as lower IL-4." (PMID 34649076, 2021). "IL-10 from innate cells has previously been shown to reduce B. pertussis-specific pro-inflammatory responses in infants that received an acellular pertussis vaccine." (PMID 34649076, 2021). "Genotype frequencies and OR for the VDR, TNFα, IL17, MBL2 and IL10 SNPs in the pertussis patient group and control group." (PMID 26894582, 2016). "Single-nucleotide polymorphisms (SNPs) in candidate genes, MBL2, IL17A, TNFα, VDR, and IL10 were genotyped in a unique Dutch cohort of symptomatic clinically confirmed (ex-)pertussis patients and in a Dutch population cohort." (PMID 26894582, 2016). "Our findings demonstrate that immunization with licensed pertussis vaccines induces antigen‐specific CD8+ Treg cells that secrete IL‐10, which, together with CD4+ Treg cells, suppress activation of IL‐17‐secreting T cells, known to play a crucial role in protective adaptive immunity to B. pertussis." (PMID 40629997, 2025). "Our data suggests that maternal Tdap-IPV vaccination in pregnancy has a longer lasting effect on the IL-10 response to B. pertussis in the offspring, which may play a role in inhibiting pertussis vaccine responses in infants." (PMID 34649076, 2021). "Pertussis antigens contained in the Tdap-IPV vaccine have been previously shown to induce cytokine production in vitro; FHA induces TNF-α production in human monocyte-derived macrophages and stimulates the production of IL-10 and IL-6 in mouse macrophages and DCs." (PMID 34649076, 2021). "Our study suggests that IL-10, a product of regulatory T cells as well as macrophages, may play a role in maintaining the stability of persistent NTM disease as has also been suggested in the case of Bordetella pertussis infection." (PMID 21931831, 2011).
Pleural effusion (13 papers, 2015 to 2025). The presence of an excessive amount of fluid in the pleural cavity. "However, IL-10 has been shown to be increased in DHF patients associated with the degree of plasma leakage quantified by the size of the pleural effusion." (PMID 25722892, 2015). "In this study, we also evaluated the availability of 12 serum cytokines within 48 h of symptom onset to predict AP patients with pleural effusion, and IL‐1β, IL‐6, IL‐8, and IL‐10 all showed good predictive value." (PMID 38411379, 2024). "Srikiatkhachorn suggested IL-10 is a potential marker of severe disease as its measured levels are correlated positively with the size of pleural effusion in the defervescence phase." (PMID 31572634, 2019). "Research findings also include significantly elevated levels of IL-10 in pleural effusions compared to blood samples, which may imply a specific role for IL-10 in the formation of pleural effusions." (PMID 37533789, 2023). "Similarly, there was no significance in correlation between frequency of Tregs and concentration of IL-10 in any group of pleural effusions separately (MPEs with malignant cells: p = 0.227; MPEs without malignant cells: p = 0.193; nMPEs: p = 0.364)." (PMID 29785404, 2018). "IL-6, IL-8, IL-10, TNF (p<0.0001) levels were significantly higher in pleural effusion compared to plasma." (PMID 39737183, 2024).
pneumococcal pneumonia (13 papers, 2012 to 2024). A febrile disease caused by STREPTOCOCCUS PNEUMONIAE. "In a study by Endeman and colleagues, the levels of pro-inflammatory cytokines (IL-1 receptor antagonist, IL-6, IL-8 and IL-10) were found to be influenced by the nature of the causative microorganisms, with pneumococcal pneumonia being significantly associated with higher levels." (PMID 34071031, 2021). "T regulatory cell-derived IL-10 has an important role in determining resistance or susceptibility to infection against a range of pathogens and has been shown to influence susceptibility to disease in pneumococcal pneumonia." (PMID 22563306, 2012). "Here we observed that transferred WT neutrophils restored IL-10 levels in BALF to similar levels observed in control WT mice, reinforcing the idea that neutrophils are an important source of IL-10 during pneumococcal pneumonia." (PMID 33995357, 2021). "This fact has also been observed in a recent study showing that natural killer (NK) cells play a crucial role in pneumococcal pneumonia through IL-10 production, promoting bacterial growth and invasion to other host tissues after infection." (PMID 33995357, 2021). "This background contrasts with our findings and lead us to propose that the role of neutrophils as the dominant source of IL-10 production is a distinctive feature of pneumococcal pneumonia." (PMID 33995357, 2021). "Macrophages and PMNs, upon recognition of S. pneumoniae, are important producers of IL-10 in pneumococcal pneumonia." (PMID 34589087, 2021). "Identification of the signals that trigger the early IL-10 production in pneumococcal pneumonia remains unaddressed." (PMID 33995357, 2021). "After the evaluation of the contribution of neutrophils to IL-10-production during pneumococcal pneumonia, we characterized two neutrophil subsets based on their difference in size (FSClow: small or N1; FSChigh: large or N2)." (PMID 33995357, 2021). "Our results demonstrated that the modulation of the three cytokines (IFN-β, IFN-γ, and IL-10) are necessary to achieve protection against secondary pneumococcal pneumonia." (PMID 28848552, 2017). "Previous data also indicated a beneficial role for IL-10 as an adjunctive therapy to antibiotics against pneumococcal pneumonia in mouse model." (PMID 24565171, 2014). "Of several pneumococcal pneumonia-related molecular pathways with anti-inflammatory actions, we chose to focus on IL-10 as a representative of cytokine in this class." (PMID 24565171, 2014). "To conclude, the expression of KLF4 in monocytes/macrophages and PMNs might reduce the release of IL-10 in patients with pneumococcal pneumonia and, thereby, strengthen the early innate immune response against S. pneumoniae." (PMID 34589087, 2021). "Finally, our in vitro and in vivo data determined the unrecognized role of IL-10-producing neutrophils in pneumococcal pneumonia." (PMID 33995357, 2021). "In addition, it was found that IL-10 potentiated LPS-mediated Lcn2 gene expression in macrophages and that Lcn2 skewed the cells toward a deactivated phenotype via induction of IL-10 in mice with pneumococcal pneumonia." (PMID 31375129, 2019). "The finding that pneumococcal pneumonia induces IL-10 production in the lung is a significant one." (PMID 22563306, 2012). "Thus, in line with our in vitro findings, in vivo expression of KLF4 in myeloid cells increases the release of the pro-inflammatory cytokines TNF-α, KC and IL-1β and decreases the release of the anti-inflammatory cytokine IL-10 in murine pneumococcal pneumonia." (PMID 34589087, 2021). "Therefore, the present finding indicated that in the presence of concurrent treatment with AMP + AZM may lead to elevated circulating IL-10 that might influence bacterial outgrowth, suggesting that only in the latter phases of pneumococcal pneumonia is IL-10 essential for host defense." (PMID 24565171, 2014).
pneumococcal pneumonia (continued). "Since cytokines are important regulators of the host immune response during pneumococcal pneumonia we measured levels of the following cytokines in lung homogenates and plasma: TNF-α, IL-6, IL-10, IL-12p70, IFN-γ, MCP-1 and KC." (PMID 25366058, 2014). "Of note, the treatment of pneumococcal pneumonia with the Annexin A1 peptide Ac2-26, a pro-resolving mediator, did not increase IL-10, while reducing the inflammatory response, lung damage, bacterial loads and increasing phagocytosis." (PMID 35159341, 2022). "On the contrary, here we provide new insights of neutrophil characteristics in the early stage of pneumococcal pneumonia, where IL-10-producing neutrophils have not been described previously." (PMID 33995357, 2021).
pulmonary edema (13 papers, 2012 to 2024). Accumulation of fluid in the lung tissues causing disturbance of the gas exchange that may lead to respiratory failure. "In a male neonate with pulmonary edema, the cytokines IL-6, IL-8, IL-10, IL-13, IL-17, and IFN-γ rises sharply during the first few hours after birth and then decreases significantly." (PMID 35725416, 2022). "The plasma levels of IL-10 in EV71-infection with pulmonary edema were very higher than those in nervous system dysregulation and brainstem encephalitis group, suggesting that increased IL-10 may have a protective effect in the development of PE by influencing the pulmonary capillary permeability." (PMID 32089650, 2020). "Reduced lung inflammation and pulmonary edema.Reduced MPO activity and IL-1β level.Increased IL-10 level." (PMID 32519302, 2020). "In our study, we firstly showed that EGCG pretreatment significantly improved hypoxemia and histopathologic changes, alleviated pulmonary edema and lung vascular leak, reduced the level of TNF-α and IL-1, and increased the production of IL-10 in seawater aspiration-induced ALI rats." (PMID 24692852, 2014).
relapsing-remitting MS (13 papers, 2006 to 2024). "A reduction in IL-10 producing B cells was found in relapsing-remitting MS (RRMS) patients experiencing relapse compared with patients in remission." (PMID 31244763, 2019). "Vitamin D supplementation trials in MS patient cohorts have shown that high dose vitamin D elevates the proportion of IL-10 producing CD4+ T cells, increases levels of cell proliferation, and leads to a global increase in IL-10 levels in the serum of relapsing remitting MS patients." (PMID 37600781, 2023). "In addition, there is a significant decrease in IL-10-producing B cells in patients with relapsing-remitting MS (RRMS) compared with recovering patients, as well as healthy individuals." (PMID 36591309, 2022). "HCMV serostatus was determined in 73 MS patients (55 relapsing-remitting MS (RRMS); 18 progressive MS (PMS)) and 30 healthy controls, assessing their B cell immunophenotype and cytokine production (GM-CSF, IL-6, IL-10, and TNFα) by flow cytometry." (PMID 32434524, 2020). "Furthermore, in a pilot trial, oral E3 treatment of women with relapsing-remitting MS (RRMS) caused significant decreases in the number of gadolinium-enhancing lesions on brain magnetic resonance imaging (MRI), and significant increases of IL-5 and IL-10 levels." (PMID 23674997, 2006).